TNF (tumor necrosis factor)
Diseases named in the same sentence as TNF in open-access papers (continued):
Sharing a sentence is not in itself a finding about the gene and the disease.
sarcopenia (continued). "iNOS has been proven to be an important mediator in TNFα-induced cachectic muscle loss and in age-related muscle wasting (sarcopenia)." (PMID 29854093, 2018). "High levels of circulating IL-6 correlate with the development of mobility disability and high levels of IL-6 and TNF-α, either alone or together, are linked with decreased muscle mass and strength, increasing the susceptibility to sarcopenia." (PMID 30498696, 2018). "A study on the correlation between TNF-α and sarcopenia revealed that elevated levels of TNF-α are associated with the decline in muscle mass and strength." (PMID 28701179, 2017). "Increased levels of inflammatory cytokines such as IL6 and TNF- alpha, as well as hsCRP, were associated with sarcopenia in the general population and patients with ESRD." (PMID 28448584, 2017). "Recent studies have shown that G/A-308 TNF-α polymorphism as a marker of sarcopenia in normal weight obese syndrome, suggesting the importance of TNF-α in the diagnosis of sarcopenia." (PMID 27382188, 2016). "Geriatric frailty, which is usually concurrent with sarcopenia and aging, is associated with increased inflammatory activity and is reflected by increased levels of circulating TNF-α, interleukin (IL)-6, cytokine antagonists, and acute-phase proteins." (PMID 23418545, 2013). "Elevated levels of TNF-α have also been implicated in sarcopenia, the age-related loss of muscle mass, strength, and function." (PMID 22536489, 2012). "Four studies reported the association between TNF‐α levels and sarcopenia in patients with CKD." (PMID 41457350, 2026). "For example, elevated expression of TNF-α in muscles is associated with muscular weakness; loss of muscle strength and mass is linked to worsening sarcopenia which results in degradation of skeletal muscle protein content and subsequent fatigue along with limitations on physical activity." (PMID 40852355, 2025). "The most significantly enriched gene set was the TNFα signaling pathway via NF-κB, which is interesting because tumor necrosis factor (TNFα) is known to be associated with sarcopenia with its ability to promote protein catabolism, muscle degeneration and muscle atrophy." (PMID 41321491, 2025). "Another open question is the role of biomarkers of biological aging and musculoskeletal reserve, including proteomic risk scores, low IGF-1, serum myostatin, TNF-α, and vitamin D, which may help identify individuals at risk for sarcopenia and poor recovery." (PMID 40700118, 2025). "Since sarcopenia is associated with elevated levels of IL-6, IL-17A, and TNF-α, patients with sarcopenic obesity may face a higher risk of swelling due to this combined inflammatory burden." (PMID 41233862, 2025). "Similarly, higher TNF-α levels independently correlated with increased sarcopenia risk (OR=1.380, 95% CI: 1.073–1.755, P=0.012), indicating that both IL-6 and TNF-α were independently linked to sarcopenia." (PMID 40265008, 2025). "This chronic, low-grade inflammatory state is recognized as a key pathological mechanism underlying sarcopenia, where inflammatory mediators like TNF-α and IL-6, activated through the NF-κB signalling pathway, inhibit muscle protein synthesis and accelerate muscle protein breakdown." (PMID 40678078, 2025). "IL-6 and TNF-α have been repeatedly shown to be associated with sarcopenia." (PMID 40869107, 2025). "Pro-inflammatory cytokines (e.g., interleukin-6, and tumor necrosis factor-α) may trigger nociceptors, increase pain sensitivity, and lower pain threshold, while also causing muscle catabolism, resulting in sarcopenia in older adults." (PMID 41024053, 2025). "Previous studies have demonstrated that TNF‐α and NF‐κB pathway activation promote age‐related changes and are associated with increased muscle degeneration, reduced protein synthesis and impaired muscle regeneration in sarcopenia due to muscle atrophy." (PMID 40810394, 2025).
sarcopenia (continued). "Additionally, inflammatory cytokines such as IL‐1, IL‐6, and TNF‐α, which are associated with anorexia and weight loss, are used for prognosing cancer cachexia and sarcopenia." (PMID 39764565, 2025). "Indeed, even though the link between TNF-α signaling and muscle wasting is complex, TNF-α has long been associated with inflammation, cachexia, and sarcopenia in patients." (PMID 39251827, 2024). "High levels of the proinflammatory cytokines tumor necrosis factor-α and IL-6 are associated with sarcopenia due to low GS and muscle mass and may exacerbate insulin action." (PMID 39408048, 2024). "Furthermore, increased levels of the inflammatory cytokines tumor necrosis factor-like weak inducer of apoptosis and tumor necrosis factor alpha (TNF-α) are associated with a heightened risk of sarcopenia." (PMID 39186818, 2024). "Hence, subsequent comprehensive investigations are needed to determine the efficacy of these drugs in treating sarcopenia induced by TNF-α signaling and cytokines intricately linked with cancer." (PMID 38556548, 2024). "Additionally, further studies on the association between TNF-α and sarcopenia are also needed to elucidate." (PMID 38760722, 2024). "We further found a high level of serum TNF-α and local TNF-α overexpression in GM of aged mice, supporting the commonly recognized view that chronic low-grade inflammation is a hallmark feature of aging, as well as sarcopenia." (PMID 36823174, 2023). "Interleukin 6 (IL-6) and tumor necrosis factor alpha (TNF-α) levels may be important factors associated with frailty and sarcopenia, according to a study." (PMID 36776966, 2023). "In addition, our study showed a significant association of MCR with sarcopenia, as well as fat mass indices in pre-frail older adults, with a significant increase in TNF-α and GDF-15." (PMID 37371414, 2023). "Higher TNF-α levels were also associated with sarcopenia in patients with stable COPD." (PMID 36835862, 2023). "Sarcopenia is also associated with elevated levels of TNF-α, IL-6, and C-reactive protein, suggesting that appropriate treatment for RA may also reduce the development of sarcopenia." (PMID 37239687, 2023). "In this study, serum TNF-α levels in older women with sarcopenia showed a significantly greater increase than in those without sarcopenia, suggesting that chronic inflammation is also associated with sarcopenia." (PMID 37015998, 2023). "Meanwhile, the IL-6 and TNF-α can impair muscle performance, causing sarcopenia." (PMID 37715186, 2023). "The mechanism involved is not fully understood but includes cytokine-driven hypermetabolism produced by TNF, IL-1β, and IL-6 (associated with resting energy expenditure and sarcopenia in RA patients), as well as the limitation of physical activity and insulin resistance." (PMID 38069224, 2023). "Therefore, we used TNF-α to stimulate myotubes in vitro for exploring underling mechanisms, which has been recognized as a classical in vitro study on sarcopenia." (PMID 36823174, 2023). "Previous study suggested that sarcopenia is associated with increased TNF-α levels." (PMID 35903456, 2022). "Similarly, IL‐1β and TNF‐α were positively associated (P < 0.05) with the presence of sarcopenia, while a trend existed for both IL‐6 (P = 0.06) and IL‐8 (P = 0.09)." (PMID 35080147, 2022). "However, continuous elevated levels of TNF-α lead to muscle damage, and increased levels of TNF-α are associated with the development of sarcopenia." (PMID 36499366, 2022). "Overall, TNF-α was implicated in the pathogenesis of sarcopenia." (PMID 35903456, 2022). "Moreover, a cross-sectional study indicated that higher plasma levels of TNF-α were significantly associated with a 7.6-fold increased risk of sarcopenia." (PMID 36160136, 2022).
sarcopenia (continued). "One of the diverse mechanisms known to contribute to the onset of sarcopenia is the slight but persistent increase in inflammatory mediators such as IL-1β, IL-6, and TNF-α that simultaneously impact muscle metabolism, causing wasting and loss via the mTOR pathway." (PMID 35954203, 2022). "After further correction of plasma IL-10 and IL-4 levels, increased plasma TNF-α level remains associated with sarcopenia, suggesting that immune aging may be involved in the pathogenesis of sarcopenia." (PMID 36160136, 2022). "A cross-sectional study exploring neuromuscular, peripheral pro‐inflammatory, and oxidative stress molecules as potential biomarkers associated with sarcopenia in old-aged people with hip fracture only found differences in peripheral TNF‐α levels and catalase activity." (PMID 33566325, 2021). "Notably, some studies have suggested how adipocytes, through the release of IL-6 and TNF-α, can promote the accumulation of fat mass and compromise muscle function, thus causing sarcopenia." (PMID 34093446, 2021). "TNF-α is a pro-inflammatory cytokine that is currently considered a significant factor and biomarker for sarcopenia; TNF-α has been indeed implicated in the effect of chronic inflammation on muscular metabolism leading to the age-related and progressive atrophy." (PMID 33808510, 2021). "Increased levels of TNF-alpha, IL-1, and IL-6 activate the ubiquitin-proteasome proteolytic pathway and play important roles in low-grade systemic inflammation; moreover, they have been implicated in the development of sarcopenia." (PMID 33997015, 2021). "A recent prospective study confirmed this hypothesis, suggesting an association of chemotherapy-induced sarcopenia with serum C-reactive protein, IL-8, and TNF-alpha levels." (PMID 33809587, 2021). "Finally, the beneficial effects of leucine supplementation in this trial seem unrelated to changes in inflammatory markers in blood such as leucocyte counts, reactive C- protein, IL-6 and TNF-alpha, which have all been associated with sarcopenia." (PMID 32230954, 2020). "Moreover, a 10-year clinical tracking survey also suggested that the serum concentrations of IL-1β, IL-6 and TNF-α are closely associated with morbidity and mortality in older sarcopenia patients." (PMID 32226296, 2020). "TNuF also reduces cancer-associated sarcopenia via the suppression of the serum TNF-α level." (PMID 32872195, 2020). "In particular, TNF is able to activate the nuclear factor kappa B (NF-kB) pathway in several cell types, including muscle cells where its effect is associated with the onset of sarcopenia." (PMID 33238549, 2020). "TNFα is a pro-inflammatory cytokine that is associated with the modulation of muscle tissue loss, particularly in pathological disease such as cancer cachexia and Sarcopenia." (PMID 31130871, 2019). "Our finding that slowing sarcopenia in TNF‐α‐null mice occurred while there was an accelerated loss of satellite cells also relates to our developing understanding of the relationships between satellite cell numbers and the regulation of muscle mass during aging." (PMID 30256507, 2018). "Data from the literature show that some inflammatory markers such as IL6, CRP and tumor necrosis factor (TNF) alpha were associated with sarcopenia, and in patients with CKD, these markers were higher than in the patients with normal renal function and were associated with unfavorable outcomes." (PMID 28448584, 2017). "Inducible nitric oxide synthase (iNOS) has recently been shown to be an important mediator of TNFα-induced cachectic muscle loss, and studies suggest that it may also play a role in sarcopenia." (PMID 21832306, 2011). "The analysis of E-DII with cfDNA (Classifier Accuracy 79.7%, p = 0.001) showed a higher diagnostic utility in sarcopenia prediction then conventional inflammatory markers such as IL-1β, IL-6 and TNFα, which may have important implications in defining healthy or unhealthy ageing." (PMID 41345186, 2025).
sarcopenia (continued). "This increase in oxidative stress is associated with a greater risk of sarcopenia, which is inversely related to skeletal muscle mass and correlates with elevated levels of myokines, including proinflammatory interleukin-6 (IL-6) and tumor necrosis factor-α (TNF-α)." (PMID 40243531, 2025). "Additionally, oxidative stress may drive other processes associated with sarcopenia, including proteolysis, upregulation of TNF‐α levels, and inhibition of muscle cell differentiation." (PMID 39764565, 2025). "The analysis of classifier accuracy for E-DII + cfDNA showed its higher diagnostic utility in predicting sarcopenia then conventional inflammatory markers such as IL-1β, IL-6 and TNFα, which may have important implications in defining healthy or unhealthy ageing." (PMID 41345186, 2025). "Finally, sarcopenia is related to a condition of systemic inflammation that occurs both at pre-clinical and clinical levels: it contributes to activate tumor necrosis factor (TNF) cascade and is linked to a high neutrophil to lymphocyte ratio." (PMID 38339347, 2024). "Relevant studies show that the concentration of plasma inflammatory factors (IL-6 and TNF-α) is associated with the emergence of sarcopenia in men that is more prevalent than that in women, which may be caused by estrogen inhibiting the expression of inflammation-related genes." (PMID 36615879, 2023). "Increased inflammatory factors such as IL-6, resistin, TNF-α, and ROS production are also associated with NF-KB signaling and the ubiquitin-proteasome system in skeletal muscle, both of which may be involved in the pathogenesis of sarcopenia." (PMID 35250869, 2022). "Proinflammatory cytokines, such as interleukin (IL)-1, IL-6, and tumor necrosis factor alpha (TNF-α), cause skeletal muscle proteolysis by suppressing muscle genes and activating ubiquitin-proteasome-mediated proteolysis and are closely associated with both sarcopenia and cancer-related cachexia." (PMID 32828127, 2020). "Thus, multiple mechanisms may underlie the reduction in sarcopenia in TNF‐α‐mutant mice, in addition to the effects we report concerning influences on satellite cell function and muscle cell fusion during aging." (PMID 30256507, 2018). "Network pharmacology results showed that the active ingredients of SJZD acted on 36 targets of sarcopenia, which were mainly enriched in the interleukin-17 pathway, TNF pathway." (PMID 41931359, 2026). "Sarcopenia, current corticosteroids use, as well as prior thiopurine and anti-tumor necrosis factor (TNF) exposure have been identified as additional predictors of colectomy." (PMID 41499005, 2026). "In individuals with sarcopenia, the expression levels of TNF‐α typically rise, activating the NF‐κB inflammatory pathway, leading to an increase in the release of pro‐inflammatory cytokines, exacerbating muscle inflammation and atrophy." (PMID 40255543, 2025). "First, a randomized study showed that 24-week pre-dialysis resistance training (RT) (1 h before HD, 3×/week) reduced sarcopenia and improved strength, body composition, functional performance, and biomarkers (TNFα, IL-6, anaemia)." (PMID 41126503, 2025). "The TNF‐α/NF‐κB signaling pathway plays a significant role in the onset and progression of sarcopenia." (PMID 40255543, 2025). "These markers are strongly linked to age-related morbidity and mortality: elevated CRP predicts CVD onset in older adults, and TNF-α/IL-6 correlate with sarcopenia and disability." (PMID 41561801, 2025). "The available reports on changes in concentrations of CRP, IL-1β, IL-6 and TNFα confirmed that inflammation was a critical component of sarcopenia progression." (PMID 41345186, 2025). "Multivariable logistic regression analysis indicated that patients in the sarcopenia group were positively correlated with interleukin (IL)-6 and tumour necrosis factor (TNF)-α (P<0.05)." (PMID 40265008, 2025).
sarcopenia (continued). "To optimize the TNF‐α treatment conditions for sarcopenia modelling, we first exposed hSkMOs to varying concentrations of TNF‐α (0, 5, 10, and 20 ng/mL) for 2 days and analysed the number of PAX7+ SCs by immunohistochemistry." (PMID 40810394, 2025). "Instead, specific increases in TNF- α and IL-6 in sarcopenia levels reflect a muscle-autonomous inflammatory pathway." (PMID 41226798, 2025). "The specific increase in TNF-α in sarcopenia and the refined IL-6 levels after excluding studies with significant heterogeneity delineate the muscle-autonomous inflammatory pathway." (PMID 40507924, 2025). "Research has shown that CHI3L1 secreted by muscle cells can alleviate sarcopenia by up-regulating the tumor necrosis factor (TNF)-α/TNF-R1 signaling pathway." (PMID 40821115, 2025). "Bioinformatics analysis identified 78 biphenotypic target genes shared by LT and sarcopenia, with hub genes including IL1B, ADIPOQ, and TNF showing strong associations." (PMID 41211064, 2025). "Interleukins exert a pivotal role in sarcopenia, with elevated TNF-α, IL-6, and IL-1β levels correlating with increased mortality and morbidity among older adults." (PMID 40429815, 2025). "On one hand, cancer induces sarcopenia through mechanisms such as systemic inflammation, metabolic dysregulation, elevated catabolic cytokines (e.g., IL-6, TNF-α), and the direct myotoxic effects of chemotherapy and radiotherapy." (PMID 40661078, 2025). "Systemic inflammation—driven by cytokines such as TNF-α, IL-1β, and IL-6—is known to promote muscle catabolism and intramuscular lipid accumulation, thereby contributing to both sarcopenia and myosteatosis." (PMID 41567660, 2025). "To investigate the acute pro‐inflammatory response and intrinsic regenerative capacity of hSkMOs, we induced sarcopenia‐like conditions by TNF‐α treatment for 2 days and analysed." (PMID 40810394, 2025). "Elevated levels of IL-6, CRP, and TNF-α have been investigated as possible pathophysiological mechanisms involved in sarcopenia." (PMID 41465572, 2025). "Levels of inflammatory biomarkers like tumor necrosis factor α and interleukin 6 are relevant to frailty/sarcopenia." (PMID 40989160, 2025). "Studies have shown that sarcopenia patients often present with elevated levels of inflammatory mediators, including IL-6, TNF-α, and CRP32." (PMID 40664812, 2025). "In sarcopenia, pro-inflammatory myokines such as IL-6 and TNF-α are persistently overexpressed, activating the JAK/STAT and NF-κB signaling pathways, which induce and maintain a chronic low-grade inflammatory state." (PMID 41140691, 2025). "In mice with dexamethasone‐induced sarcopenia, the expression level of TNF‐α protein in muscle was significantly increased compared to the control group." (PMID 40255543, 2025). "Elevated TNF-α levels are significantly correlated with decreased muscle mass and function in inflammatory diseases, cancer cachexia, and age-related sarcopenia." (PMID 41140691, 2025). "Conversely, in sarcopenia, the levels of pro-inflammatory cytokines such as TNF- α and IL-6 are primarily elevated." (PMID 41226798, 2025). "Research has identified elevated levels of pro-inflammatory cytokines such as interleukin-6 (IL-6), interleukin-8 (IL-8), tumor necrosis factor-alpha (TNF-α), and IL-1β in individuals with sarcopenia." (PMID 40943447, 2025). "This nationally representative cross-sectional study revealed a positive correlation between exposure to mVOCs and sarcopenia via TNF and PI3K–Akt signaling pathways." (PMID 41171716, 2025). "BMI, serum ALB, FGF19, and TNF-α levels were lower in the older adults population with sarcopenia, while GDF11 was higher in the serum of patients with sarcopenia." (PMID 40969368, 2025). "A key contributor to sarcopenia is chronic inflammation by pro‐inflammatory cytokines such as TNF‐α." (PMID 40810394, 2025).